TIRAP (TIR domain containing adaptor protein)
Diseases named in the same sentence as TIRAP in open-access papers (continued):
Sharing a sentence is not in itself a finding about the gene and the disease.
venous thromboembolism (1 paper, 2022). Occlusion of the lumen of a vein by a thrombus that has migrated from a distal site via the blood stream. "No obvious differences in distribution of the TIRAP polymorphism and the occurrence of venous thromboembolism were found." (PMID 34995294, 2022).
viral pneumonia (1 paper, 2021). Inflammation of the lung parenchyma that is caused by a viral infection. "Most likely, combinedand bacterial but not viral pneumonias are associated withTLR2 and TIRAP gene variants." (PMID 35083399, 2021).
infection (25 papers, 2010 to 2026). The state of being infected such as from the introduction of a foreign agent such as serum, vaccine, antigenic substance or organism. "Last, IFN-γ training restored impaired innate responses in macrophages from individuals homozygous for the TIRAP 180L polymorphism, a genetic variant associated with increased susceptibility to infection." (PMID 41665962, 2026). "In our analysis, the TIRAP/Mal homozygous genotype influenced patient morbidity resulting in higher risk of severe infections (OR: 7.3; 95% CI: 1.89 to 28.50; P < 0.01)." (PMID 20525286, 2010). "The presence of TLR4 mutations in combination with TIRAP/Mal variants - either homozygous or heterozygous - resulted in a statistically significant increase in the risk of severe infections." (PMID 20525286, 2010). "TLR4 and TIRAP/Mal polymorphisms in 375 general surgical patients were associated with risk of infection, clinical course and outcome." (PMID 20525286, 2010). "This study aims to examine the response associated with genetic variations of TLR4, the receptor for bacterial LPS, and a central intracellular signal transducer (TIRAP/Mal) on cytokine release and for susceptibility and course of severe hospital acquired infections in distinct patient populations." (PMID 20525286, 2010). "RAW264.7 cells transfected with HA-ubiquitin, followed by infection with B. neotomae and IP of TIRAP." (PMID 37778729, 2023). "In accordance with our previous findings, successful TIRAP silencing reduced the expression of these cytokines following LPS treatment and infection by E. coli." (PMID 35884781, 2022). "BtpA has been proposed to act as a mimic of the TLR adaptor TIRAP by binding specific phosphoinositides of the plasma membrane and increasing TIRAP ubiquitination and degradation during infection." (PMID 32298382, 2020). "For this purpose we evaluated the expression of TLR-2, MyD88, IRAK4, TRAF6, and TIRAP in macrophages at 48 hr after infection with H37Rv, BCG, H37RvΔRD-1 or H37RvΔESAT-6." (PMID 24475192, 2014). "The Salmonella enteritica TlpA protein enhances bacterial survival in macrophages and mice and the Brucella TcpB protein inhibits TIRAP mediated signaling and reduces systemic spread of bacteria during the early stages of infection." (PMID 20886104, 2010). "In the first part of this study we were able to show an association between the risk of severe infections and a combination of genetic variants in sequential molecules of the LPS-sensor consisting of TLR4 and its adaptor TIRAP/Mal." (PMID 20525286, 2010). "In addition, BtpA/TcpB was also shown to bind TIRAP, which results in its increased ubiquitination and degradation during infection, which also differs from PumA which despite TIRAP binding does not induce its degradation." (PMID 28483816, 2017). "TIR-1, a TIR domain-containing adaptor protein, has been suggested to be an upstream component of the p38 MAPK pathway upon infection." (PMID 34704806, 2021). "C57BL/6, MyD88−/−, TIRAP−/− and TRIF−/− mice were injected intrastromally with Af293.1RFP conidia, and markers of infection were examined as before." (PMID 20617171, 2010). "Previous studies have highlighted the central role of TLRs in K. pneumoniae recognition with marked susceptibility to infection observed in the absence of TLR adaptors such as MyD88, TRIF, and TIRAP." (PMID 40248691, 2025). "However, upon infection with SE, we found 11 of the TLR reference genes that were significantly up-regulated in heterophils from line A when compared to line B (MD-2, TIRAP, IRAK4, TRAF3, TAK1, IKKε, IKKα, NF-κB2, PI-3K, p38, and IRF7)." (PMID 22783275, 2012). "However, an influence of infection type was observed in the remaining subgroups (TLR4, TIRAP/Mal heterozygous and wild type-patients)." (PMID 20525286, 2010).
infection (continued). "The same author noted that infection with Newcastle disease virus (NDV) stimulates the recognition of viral components by host cells, particularly the recognition of RNA by Toll-like receptor 3 (TLR3), which subsequently activates the TIRAP-dependent signaling pathway." (PMID 40655137, 2025). "Furthermore, TIRAP, ETS1, and KIRREL3 are important in modulating the immune response to NDV infection, influencing both viral replication and the host’s ability to control the infection." (PMID 40655137, 2025). "LTA -+252 and CCC, TNFA-308 and CCC, IL10-819 rs1800871 and CCC, TLR4 haplotype D229G/T399I with protection from CCC, TIRAP S180L (rs8177374) and rs8177376 (strong linkage disequilibrium) with CCC, IL18 rs360719 and infection, IL17A rs4711998 and infection, TGFB1+10 rs1800470 with infection." (PMID 40297326, 2025). "Interestingly, we did not see any impact on the overall levels of TIRAP during infection suggesting that PumA is not inducing TIRAP degradation as was previously reported for BtpA." (PMID 28483816, 2017). "However, upon infection with SE, we found a significant up-regulation in six other TLR signaling pathway genes in the heterophils from line A chickens: MD-2, TIRAP, IKKε, NF-κB2, p38 MAPK 11, and p38 MAPK 12 in addition to IRF7 when compared to line B heterophils (p < 0.01)." (PMID 22783275, 2012). "We also observed that the mRNA transcript levels of MyD88 and other proteins in the MyD88 signaling pathway (TIRAP, TRAM, TRIF, and TRAF6, not shown) are similar after low MOI infection with WT TB40/E or UL88-STOP virus." (PMID 40638072, 2025).
tumor (22 papers, 2012 to 2025). "Increased expression of IRF2, GPX4, and TIRAP, for example, has been linked to enhanced susceptibility of tumor cells to chemotherapeutic agents such as TP-3654, nelarabine, S-49076, ZM-336372, XL-147T, and tivantinib." (PMID 40535818, 2025). "HCC patients with high ALKBH5 and TIRAP expression were prone to radiation‐induced liver injury and poor tumour response to radiotherapy." (PMID 36792369, 2023). "In total, 5 of the 34 pyroptosis-related genes were related to prognosis and four of them (ELANE, GPX4, GSDMD, and TIRAP) had different expression values between tumor and normal tissues, which were, thus, chosen as prognostic DEPRGs." (PMID 34722500, 2021). "TIRAP is a key intracellular signaling molecule that regulates a variety of immune responses and plays an important role in the immune response by interacting with a range of intracellular signaling mediators, and some studies have shown that it also participates in tumor regulation." (PMID 38025749, 2023). "Additionally, treatment of HBAAV‐TBG‐shALKBH5 or/and CCR6 inhibitor markedly decreased tumour volume and liver/body weight ratio, promoted tumour necrosis and inhibited ALKBH5/TIRAP axis in tumour." (PMID 36792369, 2023). "These included transcription factor EGR1 which is reported to have tumor suppressor properties, genes involved in lymphocyte activation and differentiation such as BCL6, CD4 and SMAD3 and genes TLR3 and TIRAP that are part of the toll-like receptor signaling pathway." (PMID 23072359, 2012).
bacterial infection (10 papers, 2009 to 2022). "In addition to protection against pneumococcal disease, the TIRAP S180L variant has been associated with protection against other bacterial diseases, e.g., TB and sepsis." (PMID 29353387, 2018). "Altogether, these results indicate that TIRAP can influence IRF5-mediated TLR8 signaling also during bacterial infection, which is especially clear for the induction of IL-12A expression by GBS." (PMID 35884781, 2022). "For example, B. melitensis TcpB, described as a molecular mimicry of TIRAP, can bind with MyD88 and TIRAP via TIR–TIR interaction to promote the ubiquitin-mediated degradation of TIRAP during bacterial infection." (PMID 34305858, 2021). "Regarding the downstream of MyD88/TIRAP pathways, we subsequently investigated two structural classes of NF‐κB protein expression, which played a key role in regulating the immune response to bacterial infection." (PMID 33463070, 2021). "Other SNPs involved in the bacterial infection might be relevant in BM e.g. macrophage migration inhibitory factor (MIF) Toll-interleukin 1 receptor domain containing adaptor protein (TIRAP) and complement mediated inflammation." (PMID 22662111, 2012). "TIRAP, also known as MYD88 adapter-like (Mal), is an important link between MYD88 and the receptor complex formed by TLR2 and TLR4 activation following bacterial infection." (PMID 35140801, 2022).
cancer (10 papers, 2015 to 2025). A tumor composed of atypical neoplastic, often pleomorphic cells that invade other tissues. "The four PRGs—CASP5, CASP8, IL6, and TIRAP—in this PPS were found to be closely associated with the development of cancers." (PMID 35255915, 2022). "Furthermore, there is evidence shows that TIRAP is a risk factor of cancer prognosis." (PMID 34589498, 2021). "Overall, the NLRP3, PJVK, TIRAP, IL18, NLRP1 and NLRP6 genes were thought to protect against cancer, while the rest of the pyroptosis genes seemed to be correlated with cancer risk." (PMID 35246158, 2022). "Among these signatures (TNF, TIRAP, CASP9, PLCG1, PRKACA, CASP3, CASP8, CASP4), TNF (Tumor necrosis factor) is currently considered a two-edged sword in cancer development." (PMID 35741587, 2022). "For example, TIRAP, which is involved in the Toll-like receptor (TLR4) signalling immune system pathway, was significantly correlated with CNV in 29 types of cancers." (PMID 35246158, 2022). "The enhanced phosphorylation of NFκB in CRC cells after palmitic acid treatment suggests that the activation of the TLR4 signaling pathway is, at least in part, due to the enhanced TLR4, MyD88, and TIRAP expressions in the cancer cells but not a direct binding of palmitic acid to the TLR4 protein." (PMID 34385421, 2021).
infectious disease (5 papers, 2009 to 2022). A disorder directly resulting from the presence and activity of a microbial, viral, or parasitic agent in humans. "Recent studies on the TIRAP gene have indicated that it may play an important role in susceptibility to infectious diseases." (PMID 19693265, 2009). "TIRAP is a critical gene in the TLR2 and TLR4 signalling cascades and recent studies have investigated its role in a number of infectious diseases including TB." (PMID 19693265, 2009). "A broad protective effect of TIRAP S180L against infectious diseases per se is not discernible." (PMID 19602285, 2009).
TIRAP also shares sentences with these, for which no sentence is quoted: Chagas disease (2 papers); glioma (2); lymphocytic leukemia (2); airway hyperresponsiveness (1); alopecia (1); cardiomyopathy (1); cholesteatoma (1); Cirrhosis (1); colitis (1); E. coli infection (1); Hepatitis (1); hepatocellular carcinoma (1); herpes simplex encephalitis (1); immunodeficiency (1); Lung Injury (1); mastitis (1); mouth ulcers (1); Osteolysis (1); Parkinson (1); pneumococcal bacteremia (1); pneumococcal infection (1); pneumococcal meningitis (1); psychosis (1); pyelonephritis (1); renal cell carcinoma (1); Rotavirus infection (1); thyroid cancer (1).